ZSCAN22 (zinc finger and SCAN domain containing 22)
Description:
May be involved in transcriptional regulation.
Synonyms: HKR2; ZNF50
Tractability: PROTAC: UniProt records ubiquitination sites on it; ubiquitination databases record sites on it.
Gene: Protein-coding gene on chromosome 19 (58,326,994 to 58,342,343, forward strand). Ensembl gene ENSG00000182318.
Subcellular location: Nucleus
Subcellular location (Human Protein Atlas): Cytosol; Plasma membrane; Actin filaments
Gene Ontology:
Molecular function: protein binding; DNA-binding transcription factor activity, RNA polymerase II-specific; RNA polymerase II cis-regulatory region sequence-specific DNA binding
Biological process: regulation of transcription by RNA polymerase II
Cellular component: nucleus
Genetic constraint (gnomAD): Loss-of-function variants: 7 observed, 13.34 expected, observed/expected ratio (o/e) 0.52, 90% interval 0.3 to 0.99. The upper end of that interval is the gene's LOEUF score, 0.99, which puts it in group 4 of 6, group 1 being the genes least tolerant of losing a copy. Missense variants: 576 observed, 664.66 expected, observed/expected ratio (o/e) 0.87, 90% interval 0.81 to 0.93. Synonymous variants: 243 observed, 269.37 expected, observed/expected ratio (o/e) 0.9, 90% interval 0.81 to 1.
Homologues: Orthologues: chimpanzee ZSCAN22 (99% identical), macaque ZSCAN22 (96% identical), dog ZSCAN22 (82% identical), rabbit ZSCAN22 (80% identical), mouse Zscan22 (75% identical), rat Zscan22 (72% identical). Paralogues in human: ZKSCAN8 (42% identical), ZKSCAN3 (42% identical), ZKSCAN4 (41% identical), ZNF263 (40% identical), ZSCAN12 (40% identical), ZSCAN26 (40% identical), ZNF397 (40% identical), ZSCAN30 (39% identical), ZKSCAN1 (39% identical), ZSCAN21 (38% identical), ZNF394 (37% identical), ZSCAN31 (36% identical), and 18 more.
Diseases named in the same sentence as ZSCAN22 in open-access papers:
ZSCAN22 is named in the same sentence as 2 diseases in open-access papers, as found by Europe PMC text mining. Sharing a sentence is not in itself a finding about the gene and the disease.
ZSCAN22 shares sentences with these, for which no sentence is quoted: breast carcinoma (1 paper); tumor (1).